IRAK3 (interleukin 1 receptor associated kinase 3)
Diseases named in the same sentence as IRAK3 in open-access papers (continued):
Sharing a sentence is not in itself a finding about the gene and the disease.
bladder cancer (3 papers, 2023 to 2025). "This study found that IRAK3 expression was downregulated in bladder cancer tissues, a pattern highly consistent with that observed in prostate cancer." (PMID 40755754, 2025). "Finally, intersecting these key genes with risk-consistent genes yielded eight immune-related genes that were negatively associated with bladder cancer risk: LIMS2, TP53INP2, IRAK3, STX2, CYP27A1, IL11RA, KCNMB1, and PDLIM7." (PMID 40755754, 2025). "Subsequent box plot analysis further demonstrated significantly lower expression of six genes (LIMS2, IRAK3, STX2, IL11RA, KCNMB1, and PDLIM7) in bladder cancer cell lines, consistent with bioinformatics analysis." (PMID 40755754, 2025). "SOX-1, IRAK3, and Li-MET are characterized by detecting changes in DNA methylation within bladder cancer cells shed in urine, achieving sensitivity of 86% and specificity of 89%." (PMID 37762677, 2023). "Although no direct clinical interventions targeting IRAK3 currently exist, its potential value in bladder cancer should not be overlooked, and the gene remains a promising candidate for therapeutic development in bladder cancer treatment." (PMID 40755754, 2025). "Through integrated multi-omics analysis and experimental validation, six genes, LIMS2, IRAK3, STX2, IL11RA, KCNMB1, and PDLIM7, were selected as potential immune-related biomarkers for bladder cancer, providing promising biomarkers and therapeutic targets for personalized treatment." (PMID 40755754, 2025). "In vitro qRT-PCR validation in bladder cancer cell lines showed downregulation of LIMS2, IRAK3, STX2, IL11RA, KCNMB1, and PDLIM7, consistent with bioinformatics findings, suggesting that these genes may serve as potential therapeutic targets." (PMID 40755754, 2025). "The consistent downregulation of these genes in bladder cancer tissues was further validated using independent public datasets, and qRT-PCR experiments confirmed the differential expression of the following six genes: LIMS2, IRAK3, STX2, IL11RA, KCNMB1, and PDLIM7." (PMID 40755754, 2025).
breast carcinoma (3 papers, 2021 to 2023). "Here, we assessed the expressions of six circRNAs that have been reported to be abnormally expressed in breast cancer: circ_0108942, circ_0001785, circ-ERBB2, circ-BMPR2, circ-UBE2D2, circ-IRAK3." (PMID 34732216, 2021).
endometritis (3 papers, 2024 to 2025). An acute or chronic, usually bacterial infectious process affecting the endometrium. "Gene expression levels were considerably higher in endometritis-affected buffaloes than in resistant ones for the genes A2M, TLR2, IRAK3, CCl2, FCAMR, iNOS, ADAMTS20, KCNT2, MAP3K4, MAPK14, FKBP5, and EPHA4." (PMID 38459095, 2024).
endotoxemia (3 papers, 2014 to 2016). "IRAK3 has been shown to negatively regulate downstream TLR signaling and to mediate LPS tolerance in human models of endotoxemia." (PMID 27260481, 2016).
experimental autoimmune encephalomyelitis (3 papers, 2023 to 2025). An autoimmune demyelinating disease of the central nervous system that is produced experimentally in animals by the injection of homogenized brain or spinal cord in Freund's adjuvant. "Studies have shown that in experimental autoimmune encephalomyelitis, IRAK3 expression is increased in microglia, and mice lacking IRAK3 exhibit significantly more severe disease symptoms." (PMID 39346771, 2024).
hepatocellular carcinoma (3 papers, 2020 to 2025). A malignant tumor that arises from hepatocytes. "Mechanistic studies have shown that promoter methylation of IRAK3 is a key epigenetic mechanism underlying its silencing, a phenomenon not only observed in hepatocellular carcinoma, but also reflected by increased methylation levels negatively correlated with gene expression in gliomas." (PMID 40755754, 2025). "It was reported that circ_IRAK3 expression was elevated in hepatocellular carcinoma." (PMID 35164763, 2022). "A previous study indicated that circ_IRAK3 was upregulated in hepatocellular carcinoma." (PMID 35164763, 2022).
ischemia (3 papers, 2016 to 2023). A hypoperfusion of the BLOOD through an organ or tissue caused by a PATHOLOGIC CONSTRICTION or obstruction of its BLOOD VESSELS, or an absence of BLOOD CIRCULATION. "There was a significant positive correlation between TLR2, TLR4, IRAK3 and IRAK4 expression and the degree of ischemia as assessed by serum lactate levels and the time until return of spontaneous circulation." (PMID 27260481, 2016).
acute coronary syndrome (2 papers, 2008 to 2025). Signs and symptoms related to acute ischemia of the myocardium secondary to coronary artery disease. "Although the functionality of the genetic variant is unknown, TNFis have been shown to reduce IRAK3 expression in monocytes from patients with acute coronary syndrome in vitro." (PMID 41009564, 2025).
acute pancreatitis (2 papers, 2023 to 2025). An acute inflammatory process that leads to necrosis of the pancreatic parenchyma. "In models of disease, such as acute pancreatitis, IRAK3 deficiency results in heightened inflammation, underscoring its importance in maintaining immune homeostasis." (PMID 40918148, 2025). "The aim of this study was to investigate the regulation of the immune response in relation to the role of the endogenous inhibitor IRAK3 in two mouse models of mild and severe acute pancreatitis." (PMID 37402858, 2023).
Autoimmunity (2 papers, 2020 to 2024). The occurrence of an immune reaction against the organism's own cells or tissues. "In a preclinical setting, when studying IRAK3 function by germline gene deletion in immunocompetent mice, homozygous IRAK3 knockout did not induce abnormalities or autoimmunity." (PMID 38334625, 2024).
Cerebral ischemia (2 papers, 2018 to 2023). Restriction of arterial blood supply to the brain associated with insufficient oxygenation to support the metabolic requirements of the tissue. "Furthermore, Irak3 knockout mice exhibited more severe brain damage after cerebral ischemia compared with wild-type mice." (PMID 37180174, 2023).
depression (2 papers, 2021 to 2023). "A recent genome-wide association study (GWAS) identified a genome-wide significant locus (rs11465988) in IRAK3 for esketamine efficacy of anti-depression (i.e., percentage change in symptom severity score compared with baseline)." (PMID 37065487, 2023). "IRAK3 expression in blood was significantly associated with UPDRS parts 2 and 4, depression, and dyskinesias." (PMID 34930919, 2021).
glioblastoma (2 papers, 2020 to 2022). The most malignant astrocytic tumor (WHO grade IV). "IRAK3 expression was higher in glioblastoma multiforme (GBM), KIRC, and cholangiocarcinoma (CHOL)." (PMID 35211171, 2022).
injury (2 papers, 2010 to 2024). Damage inflicted on the body as the direct or indirect result of an external force, with or without disruption of structural continuity. "Moreover, the production of IRAK3 may be part of a compensatory response to acute brain injury, indicating that the significant elevation of serum IRAK3 levels after ICH may be linked to this protective mechanism." (PMID 39346771, 2024). "The current study supports an interaction between TLR4 and IRAK-3 signaling pathway for the over-expression and release of pro-inflammatory cytokines during ventilator-induced lung injury." (PMID 20199666, 2010).
intracranial aneurysm (2 papers, 2021). "Compared with RHOT1, IRAK3 has been revealed to be related with MAPK and NF-kappa B signaling pathway, which participate in the pathological process of intracranial aneurysm." (PMID 34336924, 2021).
leishmaniasis (2 papers, 2022 to 2024). Infectious disease that is transmitted through the bite of hematophagous female phlebotomine sand flies. "ANXA2 and IRAK3 were closely related to the glycine, serine, and threonine metabolism, glyoxylate and dicarboxylate metabolism, Leishmaniasis, propanoate metabolism, valine, leucine, and isoleucine degradation." (PMID 38277535, 2024).
lung fibrosis (2 papers, 2020 to 2025). "Interestingly, genes related to vitamin D regulation (CYP27B1), inflammation (IRAK3) and pulmonary fibrosis (MMP1) were significantly induced by both viruses." (PMID 33301474, 2020).
osteoarthritis (2 papers, 2021 to 2025). A noninflammatory degenerative joint disease occurring chiefly in older persons, characterized by degeneration of the articular cartilage, hypertrophy of bone at the margins and changes in the synovial membrane. "IRAK3 is one of eight core genes associated with osteoarthritis (OA) in patients with metabolic syndrome." (PMID 40370470, 2025). "The expression of IRAK3 was higher in RA synovium compared to osteoarthritis synovium." (PMID 40370470, 2025).
Stroke (2 papers, 2018 to 2023). Sudden impairment of blood flow to a part of the brain due to occlusion or rupture of an artery to the brain. "In experimental stroke mice, IRAK3 has neuroprotective effects, and its deletion can exacerbate neurovascular damages." (PMID 37065487, 2023). "To elucidate the effect of IRAK-M on microglia after stroke, we examined microglia activation in the cerebral cortex in the WT and Irak3 KO mice at 24 h after reperfusion." (PMID 30622459, 2018).
and joint disorders (1 paper, 2023). "In addition, this study found that RMF treatment reduced IRAK3 expression in AS mice, suggesting it as a potential biological target for RMF treatment of bone and joint disorders." (PMID 37048045, 2023).
Aortic dissection (1 paper, 2022). Aortic dissection refers to a tear in the intimal layer of the aorta causing a separation between the intima and the medial layers of the aorta. "AGFG1, MCEMP1, IRAK3, KCNE1, and CLEC4D in module M37 were highly connected and strongly linked with AD, suggesting that these genes may help understand the pathogenesis of aortic dissection." (PMID 35178459, 2022).
atopic asthma (1 paper, 2013). An asthma that is characterized by symptoms that are triggered by an allergic reaction caused by inhaled allergens such as dust mite allergen, pet dander, pollen and mold. "Two IRAK3 SNPs (rs2701653 and rs1821777) were also observed to be related to atopic asthma in a Spanish population (P = 0.034) and in a meta-analysis of Spanish and Sardinian populations (P = 0.013)." (PMID 23967269, 2013).
bladder urothelial carcinoma (1 paper, 2022). "In contrast, lower IRAK3 expression was found in more cancer types, including LIHC, kidney renal papillary cell carcinoma (KIRP), THCA, COAD, READ, KICH, PRAD, bladder urothelial carcinoma (BLCA), UCEC, BRCA, and LUSC." (PMID 35211171, 2022).
brain infarct (1 paper, 2018). "Deletion of Irak3 aggravates functional deficits, cerebral infarct volume, brain edema, and causes hemorrhage transformation and BBB disruption." (PMID 30622459, 2018).
brain injury (1 paper, 2024). Acute and chronic (see also brain INJURIES, CHRONIC) injuries to the brain, including the cerebral hemispheres, CEREBELLUM, and brain STEM. "A recent clinical study showed that, compared to healthy controls, serum IRAK3 levels were substantially elevated at admission in patients with severe traumatic brain injury." (PMID 39346771, 2024). "In patients with severe traumatic brain injury, serum IRAK3 also independently distinguished poor prognosis at 6 months after head trauma." (PMID 39346771, 2024). "Recently, it was observed that serum IRAK3 levels were significantly elevated after severe traumatic brain injury, with a strong correlation to trauma severity, and were independently predictive of poor outcomes at 6 months." (PMID 39346771, 2024). "Similarly, in a recent study of severe traumatic brain injury, rising serum IRAK3 levels were independently related to trauma severity, which was reflected by Glasgow coma scale scores and Rotterdam classification scores." (PMID 39346771, 2024). "Thus, serum IRAK3 levels may be highly correlated with illness severity and clinical outcomes after acute brain injury." (PMID 39346771, 2024).
cardiac arrest (1 paper, 2016). Cessation of breathing and/or cardiac function. "Monocyte TLR2, TLR4, IRAK3, IRAK4, NLRP3, PYCARD and IL1B were initially upregulated in patients following cardiac arrest." (PMID 27260481, 2016). "In analysis of time-dependent expression of monocyte mRNA in patients after cardiac arrest, significantly higher levels of TLR2, TLR4, IRAK3, NLRP3, and IL1B were observed in patients in the early hours after ROSC compared to the later phase." (PMID 27260481, 2016). "Nonsurvivors at 30 days had significantly lower mRNA levels of TLR2, IRAK3, IRAK4, NLRP3 and CASP1 in the late phase following cardiac arrest." (PMID 27260481, 2016). "Serum lactate levels at the time of blood sampling were significantly positively correlated with TLR2 (rs 0.570; p = 0.001), TLR4 (rs 0.369; p = 0.045), IRAK3 (rs 0.569; p = 0.001), and IRAK4 (rs 0.413; p = 0.029) monocyte mRNA levels in the early phase after cardiac arrest." (PMID 27260481, 2016).
chronic myeloid leukemia (1 paper, 2018). "In fact, monocytes from chronic myeloid leukemia and metastatic cancer patients present IRAK3 upregulation, leading to tumor formation and growth." (PMID 29617451, 2018).
Dyskinesia (1 paper, 2021). A movement disorder which consists of effects including diminished voluntary movements and the presence of involuntary movements. "ADAM32 (Hoehn and Yahr), IRAK3 (dyskinesia), LMAN1 (UPDRS part 2), and RHD (dyskinesia) passed MR-Egger intercept, Cochran’s Q and I2 tests." (PMID 34930919, 2021).
hematoma (1 paper, 2024). A hematoma is a collection of blood from a vascular structure into an extravascular space. "The combined logistic regression method merged NIHSS scores, hematoma volume, and admission serum IRAK3 levels > 99.8 ng/ml (cutoff value) into a prediction model." (PMID 39346771, 2024). "A predictive model incorporating NIHSS scores, hematoma volume, and admission serum IRAK3 levels demonstrates high discriminatory efficiency in assessing the risk of poor outcomes." (PMID 39346771, 2024). "Admission serum IRAK3 levels were independently associated with NIHSS scores, hematoma volume, and 6-month mRS scores in a multivariate linear regression model." (PMID 39346771, 2024). "The model had significantly the highest AUC compared to NIHSS scores, hematoma volume, admission serum IRAK3, and a combination of NIHSS scores with hematoma volume." (PMID 39346771, 2024). "Notably, admission serum IRAK3 levels show a strong correlation with NIHSS scores and hematoma volume and are independently associated with 6-month mRS scores and poor prognosis after ICH." (PMID 39346771, 2024). "In the current study, increased admission serum IRAK3 levels had an independent correlation with NIHSS scores and hematoma volume." (PMID 39346771, 2024). "The prediction model, which included admission serum IRAK3 levels > 99.8 ng/ml, NIHSS scores, and hematoma volume, was illustrated via a nomogram." (PMID 39346771, 2024). "Alternatively, admission serum IRAK3 of all patients was intimately and positively correlated with admission NIHSS scores and baseline hematoma volume (both P < 0.001)." (PMID 39346771, 2024). "Moreover, the model combining admission serum IRAK3, NIHSS scores, and hematoma volume demonstrated stability and clinical value in calibration and decision curve analyses." (PMID 39346771, 2024). "Conversely, the combinational use of serum IRAK3 measurements and assessments of NIHSS and hematoma volume may be a better choice for assistance with clinical work in ICH management." (PMID 39346771, 2024). "Moreover, under the ROC curve, the prognosis prediction ability was similar between admission serum IRAK3 levels, NIHSS scores, and hematoma volume." (PMID 39346771, 2024). "However, the model exhibited the highest AUC among all indicators, including admission serum IRAK3 levels, NIHSS scores, hematoma volume, and the combination of NIHSS scores and hematoma volume (all P < 0.05)." (PMID 39346771, 2024).
hypertrophic cardiomyopathy (1 paper, 2025). A condition in which the myocardium is hypertrophied without an obvious cause. "IRAK3 can promote cell apoptosis, and IRAK3 has been identified as a pyrogenic gene in hypertrophic cardiomyopathy." (PMID 40108736, 2025).
IgG4-related disease (1 paper, 2025). "IRAK3 is upregulated in IgG4-related disease manifesting in salivary gland inflammation with M2 Mφ-associated fibrosis; fibrosis was also promoted by IRAK3 in a bleomycin-induced lung injury model." (PMID 40370470, 2025).
immunodeficiency disease (1 paper, 2021). Disease in which there is a deficiency or defect in the mechanisms of immunity, either cellular or humoral. "While it is unclear how IRAK3 exerts its negative regulatory effects, these findings highlight the potential of IRAK3 as a drug target in immunodeficiency diseases and in cancer immunotherapies." (PMID 33238146, 2021).
lung diseases (1 paper, 2024). "A recent study demonstrated that nine genes (CD274, CEACAM1, CR1, FCGR1A/B, IFITM1, IRAK3, LILRA6, MAPK14, and PDCD1LG2) showed 100% sensitivity and specificity that distinguished patients with active TB from those with other lung diseases (OPD)." (PMID 38674369, 2024).
lymph node metastasis (1 paper, 2022). "High expression of circ_IRAK3 was associated with TNM grade, lymph node metastasis, and tumor size of BC patients." (PMID 35164763, 2022).
monocytic leukemia (1 paper, 2023). "The results showed that IRAK3 PROTAC effectively degraded more than 98% of IRAK3 in human monocytic leukemia THP1 cells and primary macrophages." (PMID 38213543, 2023).
necrotizing enterocolitis (1 paper, 2015). Necrotizing enterocolitis (NEC) is a devastating disease that affects mostly the intestine of premature infants. "The IRAK3 gene has been associated with necrotizing enterocolitis, which has been shown to exist in specific subgroups of HSCR patients and it determines severe long-term sequel as it is the most invalidating and life-threatening complication of the disease." (PMID 26559152, 2015).
neuroblastoma (1 paper, 2023). Neuroblastoma (NB) is the most common solid, extracranial childhood tumor. "Importantly, IRAK3 deficient mice showed enhanced response to PD-1 blockade in an ICB-refractory MYCN-driven neuroblastoma tumor model." (PMID 36757800, 2023).
pancreatitis (1 paper, 2023). Inflammation of the pancreas. "In contrast to the model of caerulein induced pancreatitis, the degree of tissue damage was significantly higher in Irak3−/− mice compared to wild type mice." (PMID 37402858, 2023). "Here we observed an aggravating effect of the IRAK3 deletion, contrary to the mild model of caerulein induced pancreatitis." (PMID 37402858, 2023). "The cell surface expression of T-cell activation markers CD25 and CD69 were significantly increased in Irak3−/− 8 h after onset of pancreatitis." (PMID 37402858, 2023). "Intrapancreatic trypsinogen activation was not different between wild type and IRAK3 deficient mice during the time course of caerulein induced pancreatitis." (PMID 37402858, 2023).
Parkinson disease (1 paper, 2024). A progressive degenerative disorder of the central nervous system characterized by loss of dopamine producing neurons in the substantia nigra and the presence of Lewy bodies in the substantia nigra and locus coeruleus. "Similarly, both protein and mRNA levels of IRAK3 are significantly elevated in neurons, and the deficiency of IRAK3 greatly exacerbates neuronal damage in a mouse model of sub-acute Parkinson's disease." (PMID 39346771, 2024).
Renal atrophy (1 paper, 2022). Atrophy of the kidney. "Likewise, the receptor of IL-1β is associated with IRAK-M (Interleukin 1 Receptor associated Kinase 3Macrophages), a biomarker for renal atrophy and interstitial fibrosis." (PMID 35684085, 2022).